ZNF141 (zinc finger protein 141)
Description:
May be involved in transcriptional regulation as a repressor. Plays a role in limb development.
Synonyms: D4S90; pHZ-44
Tractability: PROTAC: ubiquitination databases record sites on it.
Gene: Protein-coding gene on chromosome 4 (337,800 to 384,868, forward strand). Ensembl gene ENSG00000131127.
Subcellular location: Nucleus
Pathways (Reactome):
Gene expression (Transcription): Generic Transcription Pathway; Regulation of endogenous retroelements by KRAB-ZFP proteins
Gene Ontology:
Molecular function: DNA-binding transcription factor activity, RNA polymerase II-specific; RNA polymerase II cis-regulatory region sequence-specific DNA binding
Biological process: limb morphogenesis; negative regulation of transcription by RNA polymerase II; anatomical structure morphogenesis; regulation of DNA-templated transcription; transcription by RNA polymerase II
Cellular component: nucleus
Genetic constraint (gnomAD): Loss-of-function variants: 6 observed, 10.54 expected, observed/expected ratio (o/e) 0.57, 90% interval 0.31 to 1.12. The upper end of that interval is the gene's LOEUF score, 1.12, which puts it in group 4 of 6, group 1 being the genes least tolerant of losing a copy. Missense variants: 535 observed, 569.03 expected, observed/expected ratio (o/e) 0.94, 90% interval 0.88 to 1.01. Synonymous variants: 183 observed, 197.45 expected, observed/expected ratio (o/e) 0.93, 90% interval 0.82 to 1.05.
Homologues: Paralogues in human: ZNF732 (78% identical), ZNF595 (72% identical), ZNF718 (69% identical), ZNF493 (64% identical), ZNF726 (59% identical), ZNF724 (58% identical), ZNF708 (58% identical), ZNF429 (57% identical), ZNF728 (57% identical), ZNF254 (57% identical), ZNF93 (54% identical), ZNF43 (54% identical), and 164 more.
Diseases named in the same sentence as ZNF141 in open-access papers:
ZNF141 is named in the same sentence as 7 diseases in open-access papers, as found by Europe PMC text mining. Sharing a sentence is not in itself a finding about the gene and the disease. The quoted sentences say what the papers report.
NK/T-cell lymphoma (2 papers, 2021 to 2023). "Recent studies suggest that ZNF141 is a potential marker of extranodal NK/T-cell lymphoma." (PMID 37100454, 2023). "We identified four ENKTL markers (ZNF141, FCGR2C, NES and CDC27) in patients with extranodal NK/T-cell lymphoma." (PMID 34872521, 2021).
polydactyly (2 papers, 2018 to 2023). A disease characterized by the presence of polydactyly, including syndromic and non-syndromic forms. "Mutations in the ZNF141 gene have been described in one family with polydactyly and it is regarded as a tumor suppressor gene." (PMID 36349425, 2023).
developmental and epileptic encephalopathy (1 paper, 2022). An epilepsy associated with developmental impairment that may be due to either the underlying etiology or the superimposed epileptic activity, or both. "Among these four genes, mutations in the ZNF141 and CPLX1 genes are associated with autosomal recessive postaxial polydactyly type A6 and developmental and epileptic encephalopathy-63, respectively." (PMID 35440058, 2022).
cancer (2 papers, 2020). A tumor composed of atypical neoplastic, often pleomorphic cells that invade other tissues. "ZNF141 mutations could be involved into a regulation of the different glycosylation status of CEACAM 5 and 6 that are targeted by NEO-201; however, further studies are needed to better understand the presence and relevance of this mutation in human cancers." (PMID 32637350, 2020). "Although ZNF141 expression/role in cancer has not yet been clarified, overall zinger-finger proteins have been associated with tissue development abnormalities and epithelial–mesenchymal transformation." (PMID 32637350, 2020). "Although the role of ZNF141 in cancer is not clear, other zinc finger proteins are known to bind either DNA or RNA and to play a role in gene expression, post-transcriptional modification, and protein trafficking, and may correlate with metastatic process and EMT transformation." (PMID 32637350, 2020).
tumor (2 papers, 2023). "ZNF141 mRNA expression was upregulated in tumor tissues compared to that in normal tissues." (PMID 37100454, 2023).
ZNF141 also shares sentences with these, for which no sentence is quoted: head and neck squamous cell carcinoma (1 paper); meningioma (1).